GPX4 (glutathione peroxidase 4)
Diseases named in the same sentence as GPX4 in open-access papers (continued):
Sharing a sentence is not in itself a finding about the gene and the disease.
anemia (10 papers, 2020 to 2025). A reduction in the number of red blood cells, the amount of hemoglobin, and/or the volume of packed red blood cells. "Rescue experiments reveal that vitamin E is essential for preventing necroptotic cell death and suppressing anemia caused by GPX4 deletion." (PMID 39587094, 2024). "Quantification of the basic erythrocyte parameters in the peripheral blood and the bone marrow of chimeric mice with Gpx4 deficiency in erythropoietic cells revealed anemia with a compensatory increase of early erythroid precursors and reticulocytes." (PMID 34360557, 2021). "Considering that RIPK3 deletion could prevent compensated anemia in glutathione peroxidase 4 (Gpx4)‐deficient mice and BMF in Tak1mutTnfr−/− mice, we investigated whether Abin1Q478H/Q478H drives hematopoiesis defects through an RIPK3‐dependent pathway." (PMID 38009796, 2024). "GPX4 has a critical role in scavenging ROS and lipid hydroperoxides in the erythroid lineage, and a loss of GPX4 causes erythroid precursor cell death, leading to anemia." (PMID 36769414, 2023). "Among the downstream targets of NRF2, GPX4 and SLC7A11 are important markers of iron deficiency anemia." (PMID 38693581, 2024). "Mice that were fed alcohol demonstrated signs of iron overload in the liver, as well as reduced GPX4 activity, a biomarker of low-iron anemia." (PMID 39062078, 2024). "It has been shown in studies with mice that deletion of GPX4 in hematopoietic cells leads to the development of anemia and that GPX4 is essential for preventing receptor-interacting protein 3 (Rip3)-dependent necroptosis in erythroid precursor cells." (PMID 36769414, 2023). "Gpx4 is an antioxidative enzyme and anemia induced by in vivo Gpx4 expression silencing in hematopoietic cells can be partially rescued by vitamin E supplementation." (PMID 34360557, 2021). "Functional inactivation of Gpx4 gene induces necroptotic death of erythroid precursors, which leads to anemia that is partly compensated by increased extramedullary erythropoiesis." (PMID 34360557, 2021). "Mice exhibit anemia and ineffective erythropoiesis when Gpx4 is deletion." (PMID 40574855, 2025). "Notably, the first evidence of lipid peroxidation in necroptosis was demonstrated by developing a transgenic anemia animal model using GPX4 depletion." (PMID 39587094, 2024). "When the Gpx4 gene was specifically deleted in hematopoietic cells mice develop anemia and mechanistic studies employing these tissue specific knockout mice suggested that Gpx4 is essential for preventing receptor-interacting protein 3 (RIP3)-dependent necroptosis in erythroid precursor cells." (PMID 34360557, 2021). "Indeed, AA and ferric maltol (approved for the treatment of iron-deficiency anemia in IBD31) triggered epithelial LPO, Cxcl1 expression and small intestinal neutrophilic infiltration in Gpx4+/−IEC mice." (PMID 32286299, 2020). "Next, we orally challenged 8-week old WT and Gpx4+/−IEC mice with AA once daily for five consecutive days complementary to the standard chow diet in addition to iron supplementation with ferric maltol, which is approved for treatment of iron-deficiency anemia in IBD31." (PMID 32286299, 2020).
colon adenocarcinoma (10 papers, 2021 to 2025). "Up-regulation of GPX4 expression was found to be significantly associated with survival in colon adenocarcinoma (COAD) patients." (PMID 39867908, 2024). "To investigate the association of GSTA4 with macrophage ferroptosis in human CRC, we analyzed macrophage-specific expression of GSTA4 and GPX4 along with macrophage proportions in human colon adenocarcinomas (COAD) and rectal adenocarcinomas (READ) using TCGA database." (PMID 39819335, 2025). "The somatic mutation of eight risk PRGs (CASP4, GPX4, GSDMC, TLR3, NLRP1, PLCG1, IL18, and IRF1) hardly occurred in PAAD samples but were commonly observed in colon adenocarcinoma (COAD) and stomach adenocarcinoma (STAD) ones." (PMID 35000541, 2022). "Another study indicated that glutathione peroxidase 4 (GPX4) activated stimulator of interferon (STING) genes through RBM15B‐mediated m6A modification, thereby promoting an anti‐tumor immune response in colon adenocarcinoma hosts." (PMID 40066751, 2025). "However, the mechanism of GPX4 in the regulation of cancer immunotherapy of colon adenocarcinoma (COAD) are incompletely understood." (PMID 38065948, 2023). "To investigate how effective these alternative pathways are in different cellular contexts, we used human colon adenocarcinoma (CRC) cells, highly resistant to GPX4 inhibition." (PMID 36552620, 2022).
Hypertension (10 papers, 2016 to 2025). The presence of chronic increased pressure in the systemic arterial system. "For example, hypertension has been associated with cardiac iron accumulation and suppression of antioxidant systems such as GPX4 and nuclear factor erythroid 2–related factor 2 (Nrf2), potentially promoting lipid peroxidation and oxidative burden." (PMID 41363911, 2025). "In a Spanish cohort, GPX1 rs17080528 was significantly associated with CKD susceptibility (OR = 1.87, p = 0.001), and GPX4 rs713041 was associated with the hypertension incidence among CKD patients." (PMID 39857298, 2025). "In addition, other genes were found to be associated with CKD related pathologies, such as hypertension (GPX4, CYP11B2, ERCC4), cancer predisposition (ERCC2), and cardiovascular disease (ERCC2)." (PMID 31924810, 2020). "Here, we first identified that aortic GPX4 (a core regulator of ferroptosis) significantly downregulated association with VSMC novel phenotype elevation in SHR rats and hypertension patients." (PMID 35186934, 2022). "Notably, inhibition of ferroptosis by ferrostatin-1 has been demonstrated to alleviate cardiac impairments, fibrosis and pathological remodeling during hypertension by potentiating GPX4 signaling." (PMID 36771298, 2023). "GPX4, CYP11B2, and ERCC4 genes were associated with hypertension." (PMID 31924810, 2020). "In mice with high-salt-induced hypertension, there was a significant increase in the protein and mRNA expression of ACSL4 and LPCAT3, along with a decrease in GPX4 expression (p < 0.001)." (PMID 41019540, 2025).
papillary thyroid cancer (10 papers, 2021 to 2025). "GPX4 encodes a protein and protects cells against oxidative damage which plays an important role in multiple cancers, certainly including papillary thyroid cancer." (PMID 34153004, 2021). "Silencing of circKIF4A can downregulate GPX4, resulting in the proliferation and metastatic inhibition of papillary thyroid cancer cells and inhibition of tumor growth in vivo." (PMID 37332354, 2023). "CircKIF4A reportedly promotes the malignant progression of papillary thyroid cancer and inhibits ferroptosis by sponging miR-1231 and then upregulating its target gene GPX4." (PMID 37332354, 2023). "circKIF4A promotes malignant progression of papillary thyroid cancer by sponging miR-1231, GPX4 upregulation and suppresses ferroptosis." (PMID 35579738, 2022). "circKIF4A is elevated in papillary thyroid carcinoma and the circKIF4A/miR-1231/GPX4 axis plays a crucial function in tumor proliferation as well as ferroptosis." (PMID 35579738, 2022). "CircKIF4A facilitated tumor malignant progress via the miR-1231/GPX4 axis in papillary thyroid cancer." (PMID 36098705, 2022). "circKIF4A can suppress ferroptosis by sponging miR-1231 and upregulating GPX4 in the malignant progression of papillary thyroid cancer." (PMID 35652072, 2022). "All the results showed that circKIF4A was able to directly sponge miR-1231 and promote papillary thyroid cancer progression by upregulating antioxidant protein GPX4 expression." (PMID 34153004, 2021). "As a target downstream of miR-1231, GPX4 protects cells against oxidative damage which is harmful to multiple cancers, certainly including papillary thyroid cancer." (PMID 34153004, 2021). "We confirmed GPX4 was the target of miR-1231 in papillary thyroid cancer." (PMID 34153004, 2021). "By RT-qPCR analysis, we found GPX4 overexpressed in papillary thyroid cancer cell lines, detected." (PMID 34153004, 2021). "APOE suppresses ferroptosis in papillary thyroid carcinoma (PTC) via the PI3K/AKT1 pathway, elevating GPX4/FTH1 expression while reducing Fe2+ accumulation." (PMID 41390817, 2025).
rheumatoid arthritis (10 papers, 2022 to 2026). A chronic, systemic autoimmune disorder characterized by inflammation in the synovial membranes and articular surfaces. "In rheumatoid arthritis, the mTOR pathway inhibits synovial fibroblast ferroptosis by increasing GPX4 expression." (PMID 40140647, 2025). "In terms of epigenetics, methylation mediated by SAM increases ferroptosis in rheumatoid arthritis by enhancing the GPX4 promoter in response to glycine." (PMID 38965216, 2024). "In this way, M1 cell may play a crucial role in many diseases, such as alleviating early brain injury in experimental subarachnoid hemorrhage and reducing neuroinflammation or rheumatoid arthritis via the GSH/GPx4 pathway in M1 macrophages." (PMID 40438143, 2025). "Intriguingly, research in rheumatoid arthritis (RA) has revealed that Semaphorin 5A in RA synovial fluid curtails ferroptosis in RA synovial fibroblasts by tweaking the PI3K/AKT/mTOR axis to boost GPX4 levels." (PMID 40586853, 2025). "Studies have indicated that the expression of Gpx4 was decreased in synovial fluid from the patients with OA and rheumatoid arthritis (RA), which is consistent with our findings." (PMID 36439689, 2022). "Notably, we characterized Auranofin, an anti-rheumatoid arthritis drug, as a ferroptosis inducer for these SCL/NEL cells in vitro and in vivo by targeting AP-1 and decreasing GPX4 expression, suggesting a new application for Auranofin in treating enzalutamide-resistant stem cell-like AP-1High CRPC." (PMID 42215431, 2026).
type 2 diabetes (10 papers, 2022 to 2026). "Poliumoside belongs to phenylpropanoid glycoside and alleviates type 2 diabetes-related osteoporosis by suppressing ferroptosis through activation of the Nrf2/GPX4 pathway, enhancing bone mineral density and mitigating oxidative stress." (PMID 40871742, 2025). "In a previous study we found significantly lower GPx4 enzyme in myocardial tissue from type 2 diabetes patients, corresponding to greater levels of lipid peroxidation and RCS (i.e., HNE adducts) in the tissue from these patients compared with age-matched normoglycemic patients." (PMID 38348353, 2023). "It ameliorates ferroptosis by increasing antioxidant capacity with higher GSH content and GPX4 expression, while decreasing oxidative stress with lower iron deposition and lipid peroxide in pancreatic β cells; this delays the progression and development of type 2 diabetes." (PMID 40871742, 2025). "In type 2 diabetic rats, MaR1 was observed to enhance the level of NRF2 and GPX4 protein expression." (PMID 36010637, 2022).
Crohn disease (9 papers, 2020 to 2026). A gastrointestinal disorder characterized by chronic inflammation involving all layers of the intestinal wall, noncaseating granulomas affecting the intestinal wall and regional lymph nodes, and transmural fibrosis. "In Crohn’s disease, GPX4 activity is diminished, impairing its role in inhibiting lipid peroxidation and regulating ferroptosis." (PMID 40699725, 2025). "Here, the authors report that dietary polyunsaturated fatty acids trigger intestinal inflammation resembling aspects of Crohn’s disease, which is restricted by glutathione peroxidase 4 in the intestinal epithelium." (PMID 32286299, 2020). "We report that small intestinal epithelial cells (IECs) in Crohn’s disease (CD) exhibit impaired GPX4 activity and signs of LPO." (PMID 32286299, 2020).
diabetic retinopathy (9 papers, 2015 to 2026). "Evidence for the p62/Nrf2/GPX4 pathway has been reported in diverse inflammatory diseases, including intestinal ischemia–reperfusion injury, diabetic retinopathy, and liver injury, where ferroptosis is implicated in pathogenesis via oxidative lipid damage and inflammation." (PMID 41294929, 2025). "Further studies are necessary to elucidate the role of GPx4 in the neurodegenerative changes in patients with glaucoma and diabetic retinopathy." (PMID 26083388, 2015).
influenza (9 papers, 2011 to 2025). An acute viral infection of the respiratory tract, occurring in isolated cases, in epidemics, or in pandemics; it is caused by serologically different strains of viruses (influenzaviruses) designated A, B, and C, has a 3-day incubation period, and usually lasts for 3 to 10 days. "Enhancing GPX4 abundance through selenium supplementation increases antibody responses after vaccination against influenza." (PMID 37505861, 2023). "There were nosignificant effects of the influenza vaccine on platelet GPx4 activity, week 10compared with week 12 data, for any of the groups." (PMID 21445287, 2011). "Furthermore, selenium supplementation also increased GPX4 expression in human T cells and Tfh responses during influenza vaccination." (PMID 39188677, 2024). "Tfh cell numbers are regulated by GPX4-controlled cell death, and increasing GPX4 abundance through selenium supplementation may increase antibody responses after influenza vaccination." (PMID 38127902, 2023). "The Grsf1 binding site in Influenza and in Gpx4 was determined to be an A(G)3U or A(G)4A element respectively whereas a larger structure was suggested to be involved in Grfs1 binding in Gpx4." (PMID 25184340, 2014). "Additionally, it has been shown that selenium may enhance antibody response to the influenza vaccine in mice and young adults by increasing glutathione peroxidase 4 level in Tfh cells, and thereby preventing their lipid peroxidation-induced ferroptosis." (PMID 39066381, 2024). "Additionally, Se supplementation enhances the expression of glutathione peroxidase 4 (GPX4) in CD4+ T cells, increases the population of T follicular helper (TFH) cells, and further promotes immune responses following influenza vaccination in mice." (PMID 40141154, 2025). "In terms of the role of Se element, a previous study showed that selenium supplementation promoted glutathione peroxidase 4 (GPX4) expression in T cells, amplified the number of follicular helper T cells and boosted antibody responses in mice and young adults immunized with influenza vaccination." (PMID 35982036, 2022).
metabolic disorders (9 papers, 2019 to 2025). "Current markers (e.g., GPX4, lipid peroxides, and serum iron) lack specificity for DN, as they are also altered in other kidney diseases or metabolic disorders." (PMID 41425591, 2025). "Four aspects indicate metabolic disorder of iron, the amplified production of ROS and accumulation of lipid peroxide, and the consumption of glutathione peroxidase 4 (GPX4) and system Xc− (a cysteine/glutamate antiporter system)." (PMID 35210424, 2022). "Current markers (e.g., GPX4 expression, lipid peroxides, and serum creatinine) lack specificity for ferroptosis-driven disease, as they are altered in other glomerular diseases or metabolic disorders." (PMID 41425591, 2025). "Ferroptosis is triggered mainly by three metabolic disorders: excessive intracellular iron accumulation, increased lipid ROS [particularly hydroxyl radicals (OH·)], and decreased activity of antioxidant systems [especially glutathione peroxidase 4 (GPX4)]." (PMID 40170719, 2025). "Current markers (e.g., GPX4, 4-HNE, and serum iron) lack specificity for ferroptosis-driven RF, as they are also altered in other kidney diseases or metabolic disorders." (PMID 41425591, 2025). "Current markers (e.g., GPX4 expression, 4-HNE, and serum creatinine) lack specificity for ferroptosis-driven cyst progression, as they are altered in other kidney diseases or metabolic disorders." (PMID 41425591, 2025). "Ferroptosis, driven by iron-dependent lipid peroxidation through the Fenton reaction and inactivation of the GPX4/Nrf2/SLC7A11 axis, disrupts spermatogenesis under conditions of oxidative stress, environmental toxin exposure, or metabolic disorders." (PMID 40331931, 2025).
renal fibrosis (9 papers, 2021 to 2025). A final common manifestation of a wide variety of chronic kidney diseases characterized by glomerulosclerosis and tubulointerstitial fibrosis. "Smad3 mediates renal fibrosis via a mechanism associated with GPX4-dependent ferroptosis." (PMID 41079940, 2025). "Thus, in CKD patients and mice, Smad3 activation is associated with decreased GPX4 expression, which may contribute to ferroptosis and progressive renal fibrosis." (PMID 41079940, 2025). "Therefore, the deficiency in GPx4 may be involved in the occurrence and development of renal fibrosis." (PMID 39021564, 2024). "Ferroptosis is a significant contributor to renal fibrosis, with GPX4 and SLC7A11 serving as key markers, detected via Western blot." (PMID 40298655, 2025). "All these in vivo and in vitro findings reveal a protective role for GPX4 in Smad3-mediated renal fibrosis." (PMID 41079940, 2025). "Studies have indicated that treatment with bergapten can indirectly restore GPX4 levels, thus inhibiting lipid peroxidation and mitigating the progression of renal fibrosis." (PMID 40766752, 2025). "Here we report a new mechanism through which Smad3 mediates renal fibrosis by downregulating the glutathione peroxidase 4 (GPX4), a central inhibitor for ferroptosis." (PMID 41079940, 2025). "We then investigated the regulatory mechanism of Smad3 in GPX4-dependent ferroptosis during renal fibrosis in a mouse model of UUO induced in Smad3 KO/WT mice." (PMID 41079940, 2025). "As a downstream target gene of Smad3, GPX4 is negatively regulated by TGF-β via a Smad3-dependent mechanism but exerts a protective role in Smad3-mediated renal fibrosis." (PMID 41079940, 2025). "The most significant finding in this study is the discovery of a new mechanism by which Smad3 mediates renal fibrosis via GPX4-dependent ferroptosis." (PMID 41079940, 2025). "All these findings demonstrated that GPX4 is a downstream target gene of Smad3 and is protective in Smad3-mediated renal fibrosis." (PMID 41079940, 2025). "We used Western blot to investigate the involvement of SIRT1 and GPX4 in the progression of renal fibrosis." (PMID 39872048, 2024). "Conversely, elevation of GPx4 can weaken the activation of the nuclear factor κB pathway, thus alleviating renal fibrosis." (PMID 39021564, 2024). "Importantly, we also identified that GPX4 is a Smad3 target gene and functions to protect Smad3-mediated renal fibrosis." (PMID 41079940, 2025). "Consistent with the previous observation, 26, 31-34 in this study, we also detected progressive renal fibrosis in patients with IgAN and DKD and in UUO mice was associated with decreased GPX4 while increasing ferroptosis as demonstrated by high expression levels of 4-HNE and TFR1." (PMID 41079940, 2025). "Importantly, we also demonstrated that loss of GPX4 in the fibrotic kidney was associated with overactivation of TGF-β/Smad3, suggesting a Smad3-GPX4-dependent ferroptosis axis in the pathogenesis of renal fibrosis." (PMID 41079940, 2025). "To investigate whether alteration of GPX4 is associated with renal ferroptosis and fibrosis in patients with CKD, we collected kidney tissues from patients with CKD and biopsy-proven renal fibrosis, including patients with DKD and focal proliferative IgAN." (PMID 41079940, 2025). "Through comprehensive approaches using Smad3-knockout (Smad3-KO) mouse model of UUO and Smad3-KO mouse embryonic fibroblasts (MEFs), we then investigated the regulatory mechanism of TGF-β/Smad3 signaling in GPX4 expression during the development of renal fibrosis in vivo and in vitro." (PMID 41079940, 2025). "This novel finding was functionally confirmed in the UUO mice and mouse embryonic fibroblasts (MEFs) in which deletion of Smad3 protected against UUO and transforming growth factor-β1 (TGF-β1)-induced loss of GPX4, upregulation of TFR1 and 4-HNE, and progressive renal fibrosis in vivo and in vitro." (PMID 41079940, 2025).